MTOR (mechanistic target of rapamycin kinase)
Diseases named in the same sentence as MTOR in open-access papers (continued):
Sharing a sentence is not in itself a finding about the gene and the disease.
cancer (continued). "In immune cells and in cancer cells, this metabolic reprogramming is mainly regulated by the serine/threonine kinase mTOR (mammalian target of rapamycin)." (PMID 30564554, 2018). "The phosphatidylinositol-3- kinase (PI3K)/AKT/mammalian target of rapamycin (mTOR) pathway (PI3K/AKT/mTOR pathway) plays a key role in cancer." (PMID 29408858, 2018). "Rapamycin, a widely used mTOR inhibitor, has been demonstrated to be applied in cancer therapy by suppressing the proliferation of cancer cells through inducinig autophagy." (PMID 29788929, 2018). "In parallel, anti-cancer inhibitors targeting mTOR axis are currently in clinical development and must be encouraged." (PMID 30356686, 2018). "Given the important role of mTOR signalling in cancer, our findings provide new insights that will facilitate the development of intervention strategies targeting this signalling network." (PMID 29330362, 2018). "The importance of the PI3K/AKT/mTOR pathway in cancer has been known for many years but the central role of RICTOR in this pathway is only starting to emerge." (PMID 29455662, 2018). "It has been well known from several studies that PI3K/Akt/mTOR signaling cascade is often aberrantly activated in a variety of cancer types and thus is an important regulator of cell proliferation and growth." (PMID 30202243, 2018). "Rapamycin and several other mTOR targeting drugs have been used for cancers and immuno-suppressive therapies." (PMID 30011848, 2018). "These recent works highlight once more the tight link that exists in cancer cells between PI3K/AKT/mTOR axis and OGT activity." (PMID 30356686, 2018). "It is the reason that single-agent rapamycin analogues have limited efficacy in cancer as a result of incomplete mTOR inhibition." (PMID 29463831, 2018). "Aberrant activation of the mammalian target of rapamycin (mTOR) plays an important role in diseases such as cancer, leading to the therapeutic exploration of mTOR inhibitors such as RAP." (PMID 30061840, 2018). "IGF-1R is also linked to the activation of Akt/mTOR signaling and activation of JNK in cancer cells." (PMID 30213025, 2018). "It is well established that aberrant mTOR signaling is involved in many disease states including cancer, cardiovascular disease, and diabetes." (PMID 29303993, 2018). "This analysis showed that effects of JG-98 on signaling pathways are both cancer-suppressing (e.g. suppression of NF-kB) and cancer-promoting (e.g. activation of mTOR)." (PMID 29445088, 2018). "With mTOR having a prominent role in cancer progression, it is initially surprising that mTOR inhibitors have had less clinical impact to treat cancer." (PMID 29301334, 2018). "Specifically, the downregulation of miR-144 leads to poor prognosis of cancer patients via activation of the mTOR signaling pathway." (PMID 30305865, 2018). "While HSA is exceedingly rare in humans, the PI3K/Akt/mTOR pathway has also been shown to be upregulated in numerous human cancers, suggesting a potential for translational implications for studies performed with canine models." (PMID 30011343, 2018). "Our multipronged strategy not only targets PI3K/AKT/mTOR pathway at multiple levels to inhibit the cancer cell proliferation, but also induces apoptosis through PAC pre-treatment (i.e., 24 h prior to EVE/DAS)." (PMID 29765318, 2018). "Frequent hyperactivation and deregulation of the phosphoinositide 3-kinase (PI3K)/ AKT/ mammalian target of rapamycin (mTOR) pathway in cancer has made it one of the most investigated therapeutic targets in tumor therapy." (PMID 29357370, 2018). "The PI3K/Akt/mTOR cascade is an important signal transduction pathway involved in most hallmarks of cancer: cell survival, motility, metabolism, and genomic instability." (PMID 29716528, 2018).
cancer (continued). "On the other hand, previous studies have reported that Akt/mTOR signaling pathway played a critical role in various biological processes of cancers, such as proliferation, metastasis, survival, and angiogenesis." (PMID 30250022, 2018). "Genetic and epigenetic alterations of both proto-oncogenes and tumor suppressor genes in the upstream of mTOR bestow it one of the most frequently deregulated signaling pathways in human diseases, especially in cancer." (PMID 29362480, 2018). "Recent studies have shown that PI3K and its components are frequently mutated in human cancers which in turn contribute to the aberrant activation of the PI3K/AKT/mTOR pathway in cancer." (PMID 29558998, 2018). "Research is ongoing to test the possible benefit of inhibiting Met or PI3K/Akt/mTOR for cancer therapy." (PMID 30406111, 2018). "mTOR is the master regulator of cell growth control, where oncogenic mTOR signalling through both complexes commonly occur in cancer." (PMID 29301334, 2018). "Ormeloxifene, in its native form or in nanoparticle encapsulated form, has been demonstrated to suppress Akt/mTOR signalling in order to exert anti-cancer activity." (PMID 29396506, 2018). "This enhanced CRC cell sensitivity to mTOR inhibition is further indicative of an important role of mTOR in cancer cell proliferation and progression." (PMID 30111296, 2018). "Although mTOR inhibitors are promising drug for cancer treatment and immunosuppressant, an unmet clinical trial is essential for their therapeutic use in cardiovascular diseases." (PMID 30305865, 2018). "The limited effectiveness of mTOR targeting was initially explained on the basis of the activation of compensatory signaling pathways unleashed by mTOR inhibitors in cancer cells." (PMID 29949919, 2018). "In cancer, mTOR signaling is highly activated, and the regulation of this signaling, as an anti-cancer strategy, has been emphasized." (PMID 29849119, 2018). "As PI3K-Akt-mTOR pathway has dual effect on chemosensitivity in cancer cells, activity of PI3K-Akt-mTOR pathway in response to cisplatin or/and NVP-BEZ235 in U2OS and Saos-2 cellscells were analyzed." (PMID 29535821, 2018). "The relationship between mTOR and LAT1 is a long lasting field of investigation also because mTOR hyper-activation is often described in cancers." (PMID 29988369, 2018). "Due to several cross-links with other pathways, secondary activation of mTOR and its pathway has also been identified as a mechanism of resistance or escape from cancer therapy, for example, in breast cancer hormone therapy." (PMID 29509701, 2018). "Throughout the years, research into signalling pathways involved in cancer progression has led to many discoveries of which mechanistic target of rapamycin (mTOR) is a key player." (PMID 29301334, 2018). "Amino acids are used in the machinery of mTOR (mechanistic target of rapamycin), which is also altered in cancer." (PMID 30532780, 2018). "This increase of integrin signaling has been shown to also upregulate the PI3K/AKT/mTOR pathways and possible metabolism switching in cancer cells." (PMID 30459440, 2018). "The molecular mechanisms regulating mTOR kinase are still poorly understood, although its constitutive activation has been repeatedly observed in cancer lesions." (PMID 30138330, 2018). "The PI3K-Akt-mTOR pathway provides unique opportunities for anticancer therapy, because it is often constitutively activated in human cancer cells." (PMID 29760955, 2018). "PIM kinase interaction with the PI3K/AKT/mTOR signaling network is confirmed, and their downstream components have shown a close connection with each other in several cancer cells." (PMID 29401696, 2018).
cancer (continued). "Quite interestingly, while contributing to cancer initiation and progression, prolonged mTOR stimulation in normal cells can paradoxically lead to stem cell depletion, reduced health and lifespan." (PMID 29351204, 2018). "Recent studies reported involvement of the AMPK/mammalian target of rapamycin (mTOR) pathway in the induction of various cancers." (PMID 30405532, 2018). "It is known that the mTOR pathway is activated during various cellular processes such as tumor formation and is deregulated in cancer." (PMID 29505855, 2018). "It is reported that G0/G1 arrest in cancer cells is induced by inhibition of the PI3K/AKT/mTOR pathway." (PMID 29614812, 2018). "Dysregulation of various components of mTOR signaling pathway has been reported in various cancers such as breast, ovarian, renal, colon and head and neck cancers." (PMID 30154572, 2018). "The active fraction induced autophagy and Bax mediated apoptosis suggesting that mTOR inhibition resulted in programmed cell death of cancer cells." (PMID 29434241, 2018). "Recent research findings also indicate that the components involved in mTOR pathway are regulated by miRs in cancer and other diseases." (PMID 30305865, 2018). "Given the inability of rapamycin and its analogues to inhibit all mTORC1 functions, and its limited efficacy in inducing autophagy as anti-cancer therapy, several compounds inhibiting the kinase activity of mTOR were then developed." (PMID 29329237, 2018). "It has also been regulated by PIM kinases in other cancers but the exact mechanism of mTOR and PIM kinases interactions in OC is still debatable." (PMID 29401696, 2018). "As SEA4 was able to induce autophagy and apoptosis in cancer cells, we investigated the status of mTOR (mechanistic target of Rapamycin), a serine/threonine kinase known to be a major effector of cell growth and proliferation." (PMID 29434241, 2018). "Although several studies established a clear synergistic effect of miRNA and mTOR in the treatment of cancer, there are scarce reports of clinical trial in cardiovascular field." (PMID 30305865, 2018). "Another study, investigating a combination of metformin and the mTOR inhibitor temsirolimus, also observed modestly promising anti-tumor efficacy in a cohort with heavily pretreated patients with advanced cancer." (PMID 28616837, 2018). "This review provides a brief and up-to-date narrative on the regulation of mTOR function, the relative contributions of mTORC1 and mTORC2 complexes to cancer development and progression, and prospects for mTOR inhibition as a therapeutic strategy." (PMID 29351204, 2018). "Weight loss can be a surrogate for overall health in patients undergoing anti-cancer therapy, and mTOR inhibition has the potential to alter the metabolism of both normal and cancer cells." (PMID 30410720, 2018). "Taken together, our data demonstrate that metformin inhibits TGF-β1-induced EMT-like process and cancer stem-like properties in GBM cells via AKT/mTOR/ZEB1 pathway and provide evidence of metformin for further clinical investigation targeted GBM." (PMID 29467947, 2018). "Not only are these natural products extremely safe in vivo, but they also function through a unique mechanism of action leading to the simultaneous and selective inhibition of key regulatory pathways including Notch/PI3K/Akt/mTOR/NF-κB in cancers." (PMID 29581860, 2018). "Non-canonical Wnt pathways have also been shown to play important roles in cancer cell metabolic reprogramming through crosstalk with the protein kinase B/mechanistic target of rapamycin (AKT/mTOR) pathway." (PMID 29463061, 2018).
cancer (continued). "Several previous studies indicated that the Akt/mTOR signaling pathway plays important roles in the regulation of cell proliferation, autophagy, and apoptosis in several malignant tumors." (PMID 30429828, 2018). "In the past few years, many new insights into mTOR function and regulation have been gained and extensive genetic and pharmacological studies in mice have enhanced our understanding of how mTOR dysfunction contributes to several diseases, including cancer." (PMID 29351204, 2018). "The role of mTOR in cancer and aging is well recognized and documented with numerous scientific publications." (PMID 30305865, 2018). "KEGG pathway analysis indicated that the cancer-associated miRNAs were involved in pathways related to cancers, such as the HIF-1 signalling and the mTOR signalling pathways." (PMID 30381359, 2018). "Here, we build a mechanistic ordinary differential equation model describing the interactions between commonly mutated pan-cancer signaling pathways—receptor tyrosine kinases, Ras/RAF/ERK, PI3K/AKT, mTOR, cell cycle, DNA damage, and apoptosis." (PMID 29579036, 2018). "RCC is a kind of cancer characterized by the over-activation of AKT/mTOR pathway and concomitantly reduced expression level of PTEN." (PMID 29665787, 2018). "The key role of mTOR in controlling cell proliferation has raised the interest in rapamycin for cancer therapy." (PMID 29932116, 2018). "Since mTOR signaling confers resistance to several targeted cancer therapies, in recent years focus has shifted towards the development of mTOR-inhibition based combination therapies." (PMID 29351204, 2018). "In general, mTOR and S6Ks, known mediators of mTOR signaling, have been related to cancer progression in several cancer models." (PMID 29805774, 2018). "It indicated that these blockades of EGFR and its downstream signal pathways further decreased the expression of PD‐L1 on cancer cell membranes by inhibiting the activity of mTOR signal pathway." (PMID 29533017, 2018). "NVP-BEZ235 or BEZ235 is a dual inhibitor of adenosine triphosphate (ATP)-competitive phosphoinositide 3-kinase (PI3K)/mammalian-target-of-rapamycin (mTOR) and is promising for cancer treatment." (PMID 30423811, 2018). "This review presents current understanding of the role of mTOR in NET tumorigenesis, beginning from mTOR functions in normal cell and common deregulation events occurring in cancer." (PMID 29509701, 2018). "Here, we review the role of mTOR in cellular processes involved in cancer cachexia and highlight the studies supporting the contribution of mTOR in cancer cachexia." (PMID 30061533, 2018). "While checkpoint and mTOR inhibitors have revolutionized cancer treatment, as monotherapies these drugs seem to be insufficient to fully block cancer progression." (PMID 29662490, 2018). "This special issue on mammalian target of rapamycin (mTOR) explores the importance of mTOR in cell growth control and cancer." (PMID 29848950, 2018). "It was reported that activation of the mTOR pathway inhibited autophagy, indicating that some miRNAs can affect the process of cancers by regulating autophagy via the mTOR pathways." (PMID 30266744, 2018). "Many studies focused on the pathogenic role of the Akt pathway and the mechanistic target of Rapamycin (mTOR) complex in mediating the progression of various types of cancer, which designates the Akt/mTOR signaling pathway as a master regulator for cancer." (PMID 30323898, 2018). "The central role of mTOR in regulating many diseases, including fibrosis and cancer, therefore establish it as a highly valuable target for manipulation." (PMID 29518028, 2018). "This metabolic reprogramming is coordinated by the mechanistic target of rapamycin (mTOR), a critical regulatory kinase that serves as a key checkpoint and therapeutic target for several cancers and inflammatory and autoimmune disorders." (PMID 29445452, 2018).
cancer (continued). "To elucidate the potential existence of mTOR-PGAM1 cascade in human cancers and its clinical relevance, we examined the relationship of mTOR activity and PGAM1 expression in human non-small cell lung cancer (NSCLC) samples." (PMID 29362480, 2018). "A review of cancer by Wouters and Koritzinsky (2008) highlights two hypoxia signaling pathways: regulation of the mammalian target of rapamycin (mTOR) and the unfolded protein response (UPR)." (PMID 30089028, 2018). "In this context, PA needs to be broken down into its main components: frequency, intensity, time, and type; however, the dose-dependent effects of each of these components on cancer protection via mTOR inhibition are still unclear." (PMID 30363988, 2018). "As a consequence, the outcomes of mTOR inhibition in cancer models are discordant and possibly dependent on the immune cell populations that are dominant in each experimental model." (PMID 30123774, 2018). "As proteasomal activity is essential for ordered progression through the cell cycle, and as the proteasome is regulated by mTOR signaling and is a potent drug target in human cancers, we decided to study the proteasome in more detail." (PMID 29669860, 2018). "Protein synthesis is frequently dysregulated in cancer and contributes to resistance to therapeutic drugs, particularly mTOR inhibitors, by allowing the continued translation of a subset of mRNAs involved in cell proliferation." (PMID 30138450, 2018). "Briefly, we found 34 somatic alterations, including eight genes recorded in the cancer gene list, and confirmed recurrent NOTCH1 (SNVs 6/9, indels 1/9), KRAS (SNVs 1/9), NRAS (SNVs 2/9), FBXW7 (SNVs 2/9), and MTOR (SNVs 2/9) mutations (Table EV1)." (PMID 29880602, 2018). "The mTOR inhibitor rapamycin is also being studied as a cancer drug, both pre-clinically and clinically, but its efficacy is reported to vary with different cancer types." (PMID 30250638, 2018). "Recently NOD-like receptor family CARD domain containing 3 (NLRC3) has been identified as the upstream negative molecule in PI3K/Akt/mTOR signaling axis to inhibit the activation of PI3K, Akt and mTOR in cancer." (PMID 29881349, 2018). "The enriched categories of target gene pathways included, microRNAs in cancer, mTOR signaling pathway, NOD-like receptor signaling pathway, NF-κB signaling pathway and others." (PMID 29685146, 2018). "Due to the relevance of MAPK-PI3K/mTOR cross-talk in cancer therapeutics, the extensive and dynamic cross-talk between these signaling pathways is now becoming clear." (PMID 29351204, 2018). "The mechanistic investigation using inhibitors targeting AKT and mTOR revealed that AKT/mTOR signalling activation is important for the oncogenic effect of EpCAM on cell invasion and stem-like properties of cancer cells." (PMID 29305578, 2018). "On the other hand, MET can inhibit the protein synthesis and cancer cell proliferation through modulation of the vital AMPK/mTOR/p70S6K pathway." (PMID 30483391, 2018). "The PI3K/AKT/mTOR signaling pathway is a central regulator of both normal and cancerous cell physiology that is altered in many human cancers." (PMID 29401696, 2018). "Emerging reports have indicated that many flavonoids mediate autophagy in cancer and that kaempferol mediates autophagy via AMPK/mTOR signaling in cancer cells." (PMID 30158521, 2018). "Other cancer drugs included the mTOR inhibitor Everolimus, the taxane Paclitaxel and differentiation inducers including a histone deacetylase inhibitor (Vorinostat) and an all-trans retinoic acid (Tretinoin)." (PMID 29755686, 2018). "The results showed that many target genes were involved in the signalling pathways of cancer progression, such as the mTOR signalling pathway, the HIF-1 signalling pathway and the calcium signalling pathway." (PMID 30381359, 2018). "For example, the signaling pathways that activate mammalian target of rapamycin (mTOR) are altered in many human cancers." (PMID 29303993, 2018).